INS (insulin)
Diseases named in the same sentence as INS in open-access papers (continued):
Sharing a sentence is not in itself a finding about the gene and the disease.
diabetes (continued). "Stanniocalcins are expressed in the pancreatic islets, where STC1 colocalizes with insulin in beta-cells and STC2 with glucagon in alpha-cells, where they are suggested to exert effects on glucose homeostasis and to be markers of the appearance and progression of diabetes." (PMID 38712328, 2024). "The contribution of both soluble and insoluble fibers in the reduction of insulin resistance and insulin levels could aid in the treatment or prevention of hypertension in individuals with or without diabetes." (PMID 39479650, 2024). "Maturity-onset diabetes of the young (MODY) is a clinically heterogeneous group of monogenic defects in beta‐cell function characterized by onset at young age, nonketotic diabetes that usually does not require insulin, and an autosomal dominant mode of inheritance." (PMID 39420905, 2024). "Morbidly obese patients with CKD who do not require insulin most likely have residual beta cell mass, and their diabetes could be reversed by bariatric surgery." (PMID 39364120, 2024). "Her diabetes mellitus shows persistent poor glycemic control during basal-bolus insulin therapy, despite the fact she is currently on Flash Glucose Monitoring (FGM) which so far has been preferred to an insulin pump because of her persistent language barrier and inability to manage the device." (PMID 38294658, 2024). "However, most hospitals do not have a designated team (i.e., diabetes stewardship) to assess and adjust insulin regimens (e.g., sliding scale intensity, dose, etc.)." (PMID 38919469, 2024). "Most diabetic patients fall into two main categories: type 1 diabetes mellitus (T1DM), caused by a severe or near-complete lack of insulin due to genetic causes, and type 2 diabetes mellitus (T2DM), characterized by insulin resistance and inadequate compensatory insulin secretion." (PMID 38891933, 2024). "A total 667,567 sensors from 22,006 CGM users were available for analysis, with 13,213 users with T1 diabetes, 5937 users with T2 diabetes treated with basal-bolus insulin/pump, 1281 users with T2 diabetes treated with basal only insulin, and 1575 T2D users not on insulin therapies." (PMID 38444315, 2024). "Type 2 Diabetes Mellitus (T2DM), an important public health problem worldwide, is a chronic metabolic disorder that results in hyperglycemia that develops due to impaired insulin secretion by the β-cells of the pancreas or the failure of insulin-sensitive tissues to respond to insulin." (PMID 38767826, 2024). "Moreover, as these indices are not dependent on insulin measurements, they are instrumental in patients with diabetes, especially those on insulin therapy." (PMID 39720248, 2024). "Some studies point towards insulin as a metabolic effector targeting the cardiomyocytes and fetal echocardiography to screen for possible birth defects is advised regardless of the type of diabetes." (PMID 39091986, 2024). "This study also did not collect information on new start insulin, just whether or not patients were on diabetes medications at baseline." (PMID 39211672, 2024). "Clove is reported to improve insulin sensitivity, inhibit aldose reductase, prevent diabetic complications such as neuropathy and nephropathy, regulate SIRT1 to enhance glucose metabolism, and promote muscle glucose uptake, all of which assist the management of diabetes." (PMID 39519546, 2024). "However, controlling for insulin does not change the significance of the effects of diabetes and exposure on bone concentrations and ratios observed in the larger subgroup." (PMID 38711110, 2024). "Moreover, the likelihood of timely basal insulin initiation (primary outcome), but not attainment of HbA1c<7% (53 mmol/mol) with insulin (secondary outcome), increased more than twofold if access to a diabetes nurse." (PMID 38116986, 2024). "Moreover, GLUTs can be insulin-dependent (e.g., GLUT 4 in skeletal muscle), which may result in reduced [18F]FDG uptake in patients with diabetes due to an insulin resistance of the cells." (PMID 38383743, 2024).
diabetes (continued). "Also, there was no diabetes stewardship team to monitor BG and modify insulin therapy, which is relevant since achieving euglycemia in BBIR patients requires more dose adjustments." (PMID 38919469, 2024). "MEG3 is downregulated in the islets and blood of individuals with diabetes, and in a murine β-cell line (MIN6), MEG3 seems to regulate insulin synthesis and secretion since its absence reduced the expression of key factors for β-cell function (PDX-1 and MAFA), decreasing insulin synthesis." (PMID 38326874, 2024). "Therefore, we aimed to compare hormonal and symptom responses to hypoglycaemia in people without diabetes and people with type 1 diabetes and insulin-treated type 2 diabetes, using a similar clamp protocol." (PMID 38376580, 2024). "In this study, in which we directly compared hormonal and symptom responses to hypoglycaemia, we found that people with type 1 diabetes had blunted glucagon and adrenaline responses to hypoglycaemia compared to those with long-standing insulin-treated type 2 diabetes and those without diabetes." (PMID 38376580, 2024). "Utilizing data from the Ludwigshafen Risk and Cardiovascular Health (LURIC) study, we assigned 917 participants without diabetes to prediabetes clusters, using oGTT-derived glucose and insulin, high-density lipoprotein cholesterol, triglycerides, and anthropometric data." (PMID 39175055, 2024). "In the diabetes 1 dataset, the daily bolus dose of insulin taken by the patients was ranked second most important factor, while in the diabetes 2 dataset the information about the patient taking insulin or not was ranked top most relevant feature (‘Clinical feature ranking results’)." (PMID 38435625, 2024). "Although there was increased diabetes satisfaction and improvement in quality of life in youth after 12-month AHCL use in those who transitioned from MDI to AHCL, there was no improvement in psychosocial outcomes in our RCT which compared AHCL to standard insulin pump therapy." (PMID 40302968, 2024). "It directly potentiates glucose-induced insulin secretion through activating PI3K/Akt pathway, a known pathway in stimulus-secretion coupling, maintains membrane integrity and β-cell viability, sustains intra-islet β-cell store, and improves hyperglycemia in vivo in an animal model of diabetes." (PMID 39399466, 2024). "Our model reflects the dependence of Lp(a) on insulin in a physiological state and not during the progression and treatment of diabetes, when beta cells may eventually fail, insulin be of exogenous origin and insulin-sensitivity of tissues be modified." (PMID 39210428, 2024). "For women without diabetes, glucose concentrations usually remain stable during labour and insulin concentrations are depressed, although interventions during this time may alter glycaemia." (PMID 38872105, 2024). "Moreover, poorly regulated concentrations of insulin, IGF, inflammatory cytokines, and hormones like leptin and estrogen in individuals with diabetes and obesity disrupt the DNA helix and refashion the DNA damage response mechanism, causing genomic instability, a hallmark of cancer." (PMID 39692821, 2024). "The absence of insulin is central to diabetes, a condition that was once invariably lethal." (PMID 38425548, 2024). "However, 14 of them had in-hospital hyperglycemia requiring insulin therapy prescription and/or HbA1c levels within the range for pre-diabetes (5.7 to 6.4%) (result not shown)." (PMID 38498483, 2024). "Using the framework of randomized controlled clinical trials, we assessed whether postoperative hyperglycemia in kidney transplant recipients without previous diabetes diagnosis could be controlled using basal insulin therapy." (PMID 38397919, 2024). "Known glucose-lowering medication status of these donors with diabetes did not significantly correlate with any insulin-secretion parameters; however, there was an overall trend with the need for exogenous insulin and lower overall insulin secretory capacity." (PMID 38959864, 2024).
diabetes (continued). "Similarly, insulin levels were higher in the type 2 diabetes group than in controls without diabetes (546 ± 71 mE/L vs 347 ± 40 mE/L, p = 0.019)." (PMID 38376580, 2024). "Despite this, a significantly greater proportion of participants in the insulin group were not aware that BP and cholesterol control are important for controlling diabetes (31.8% and 45.5%, respectively) when compared to those in the non-insulin group (22.4% and 30.2%, respectively)." (PMID 39587498, 2024). "However, limited information is available on the effects of ICI treatment on insulin secretion in individuals without diabetes." (PMID 39722806, 2024). "Moreover, reports that do not deliver applicable outcomes, like diabetes reversal, glycemic regulation, insulin sensitivity, or weight reduction, will be omitted." (PMID 39735002, 2024). "Chronic low-grade inflammation is a key feature of diabetes, and an anti-inflammatory diet rich in fruits, vegetables, whole grains, and omega-3 fatty acids can inhibit a variety of signaling pathways (e.g., the NF-κB and JNK pathways), leading to improved insulin sensitivity and β-cell function." (PMID 38961392, 2024). "Furthermore, LRP5 is known to act as a protective factor for type-2 diabetes mellitus (T2DM), promoting insulin signaling in addition to increasing insulin production and lowering blood glucose, and the expression of LRP5 is critical for bone formation, especially osteoblasts." (PMID 38302983, 2024). "This study revealed that although insulin use can treat diabetes, it does not relieve ED in patients, and it may increase the risk of ED, but there is no causal association in itself." (PMID 39247921, 2024). "Despite the wide range of actions of insulin, is it appropriate to define the disease as characterized only by abnormal glucose metabolism, is it appropriate to set the suppression of complications as a therapeutic goal, or is it not possible to cure diabetes mellitus by normalizing insulin actions?" (PMID 39513056, 2024). "The suppression rate of 18-day UCB-Tregs to PBMCs at a 1:1 ratio was negatively correlated with the course of diabetes (r = -0.770, p = 0.015) but not with age, daily insulin dose (INS dose), insulin dose-adjusted A1c (IDAA1c), FCP, 2-h PCP, 2-h C-peptide AUC, GADA, IA-2 A, and ZnT8A." (PMID 38515175, 2024). "Comorbidities in the non-endometriosis control group were diabetes and insulin sensitivity in 5/62 (8%), constipation/IBS 9/62 (15%), and PCOS, fibroids, simple ovarian cysts, inflammatory bowel disease, collagen vascular disease, interstitial cystitis in the 2–5/62 or 3–8% range." (PMID 38792407, 2024). "Guatemalan K’iche’ only recently became a written language, and certain medical terms like ‘diabetes,’ ‘kidney failure,’ ‘insulin,’ are not part of Mayan vocabulary." (PMID 38700575, 2024). "The median duration of diabetes was 6 years, and diabetes was treated mainly with oral hypoglycemic drugs or oral hypoglycemic drugs combined with annotated insulin, while a small number used simple dietary control without taking hypoglycemic drugs or insulin injections." (PMID 39519588, 2024). "Propensity score matching could not account for duration/severity of diabetes in this platform, leading to the use of insulin treatment as an active comparator design to reduce the extent of confounding by indication." (PMID 38584180, 2024). "Characterized by the body's inability to produce or effectively use insulin, diabetes leads to elevated blood glucose levels, which, if not managed, can result in severe complications such as cardiovascular disease, kidney failure, blindness, and lower limb amputations." (PMID 39839971, 2024). "Thus, ALA is considered effective in the amelioration of neuropathic impairments in elderly insulin-treated patients with history of CVD in whom weight and blood pressure are well controlled, as well as in those with more severe stages of diabetes and neuropathy, and HbA1c levels ≥7%." (PMID 38952393, 2024).
diabetes (continued). "Reports have emphasised that poor diabetic control among patients treated with insulin primarily results from a lack of understanding of the disease, a lack of knowledge of glycaemic targets, and a lack of knowledge of diabetes self-care, particularly self-insulin dose adjustment." (PMID 39020348, 2024). "Additionally, among females without diabetes, their recreational activity level was insignificantly correlated with insulin level." (PMID 39469577, 2024). "In already diagnosed individuals, there were significant differences in sex, diabetes duration, eGFR, PCS score, the number of people with retinopathy and the number of people using glucagon-like peptide-1 receptor agonists (GLP1-RAs), insulin and other glucose-lowering drugs." (PMID 38206363, 2024). "Diabetes mellitus (DM) is one of the most widespread diseases in the world, and it can be divided into type 1 diabetes, an autoimmune disorder associated with a complete lack of insulin secretion, and type 2 diabetes, which is a result of pancreatic islet β cell failure or insulin resistance." (PMID 38903628, 2024). "Our findings are supported by recent reports showing that FMT reduces postprandial glycemic responses in both T1DM and T2DM15, 17 but not by another study performed in diabetes with distal symmetric polyneuropathy showing that WMT fails to affect insulin dose or postprandial blood glucose." (PMID 37846600, 2024). "Therefore, in our opinion, caution should be taken when comparing the results of our analysis, which is based on the effect of insulin on Lp(a) concentration in non-diabetic individuals, with the results based on the assessment of insulin therapy in diabetes." (PMID 39210428, 2024). "The different clinical impacts of arm and leg muscle mass on the prognosis of diabetes may be due to the higher glucose clearance regardless of insulin resistance and better preserved insulin sensitivity in the arm than leg muscle." (PMID 39001640, 2024). "For diseases requiring daily oral medication, such as diabetes treated with oral insulin, magnetic-controlled drug delivery microrobots are not significantly competitive compared to anchored drug delivery microrobots, self-propelled and biohybrid drug delivery microrobots." (PMID 38808156, 2024). "Insulin resistance (IR), characterized by the body’s reduced ability to respond to insulin, is a hallmark of type 2 diabetes mellitus (T2DM), where insulin release may be significantly decreased or absent." (PMID 39469577, 2024). "Contrarily, other studies observed no discernible differences in insulin sensitivity in periods of 6 weeks and 24 weeks among participants with pre-diabetes (equivalent of 300 g and 150 g fresh blueberries, respectively; containing 580 mg and 364 mg anthocyanins, respectively)." (PMID 38919390, 2024). "However, diabetes-unspecific subjective stress appears not to play a major role in relation to the severity of the illness as reflected by glycemic control, insulin resistance, β-cell function, and the presence of microvascular complications." (PMID 38813430, 2024). "In a very limited number of studies specifically focused on overnight glucose levels in subjects without diabetes, a small increase in insulin concentrations and/or secretion in the face of stable or minimally elevated glucose levels has been observed toward the end of the nocturnal sleep period." (PMID 38339464, 2024). "However, it was not until the 20th century that the connection between diabetes and insulin was fully understood." (PMID 39766270, 2024). "However, the use of HOMA-IR as a measure is limited because it relies on FBG and insulin levels, which are not general clinical examinations in nondiabetic patients without diabetes." (PMID 39649228, 2024).
diabetes (continued). "Insulin Icodec, the first approved once-weekly insulin analog, provides evidence of substantial non-inferiority compared to once-daily basal analogs in diabetes management in both insulin-naïve and insulin-treated patients who failed to achieve adequate glucose control." (PMID 39200316, 2024). "Insulin itself is not a novel treatment for diabetes mellitus management." (PMID 39861067, 2024). "There have been no previous qualitative evaluations of fully automated insulin delivery systems, and this is an important aspect of research in this field, with quality-of-life impacts of diabetes technology often being as important to users as glycemic benefits." (PMID 38426909, 2024). "Without timely intervention, prediabetes can progress to diabetes, a condition characterized by elevated blood glucose due to insufficient insulin production or ineffective insulin use, leading to complications such as cardiovascular disease, kidney failure, and neuropathy." (PMID 39083543, 2024). "High rates of co-occurrent diabetes mellitus (DM) with bipolar or unipolar depression, and anhedonia in patients with DM, suggested that insulin resistance or lack of insulin may play a role in the pathophysiology of depression." (PMID 38398483, 2024). "In addition, the relative suppression of insulin secretion, along with increased levels of circulating counterregulatory hormones and increased fatty acid levels, can contribute to the development of DKA in type 2 diabetes mellitus." (PMID 39522614, 2024). "Moreover, information on the type of oral diabetes medication or dosage of insulin prescription was not explicitly described because all questionnaires were self-reported by participants." (PMID 38459065, 2024). "The BAPT prioritises patients who have had type 2 diabetes for short periods and patients without insulin requirement because the short duration of diabetes and relatively preserved pancreatic function pre-surgery are the strongest predictors of diabetes remission post-surgery." (PMID 39174748, 2024). "Both female and male VH125Tg/NOD mice have an accelerated and more highly penetrant diabetes incidence relative to the standard female (and male) NOD mice that is mediated by IFN-γ-producing insulin-specific T cells driven by the APC action of insulin-reactive B cells." (PMID 38515750, 2024). "Interestingly, the risk of biliary tract cancer (BTC) seemed to be higher in patients with shorter diabetes durations who were not treated with insulin." (PMID 39410050, 2024). "Compared with individuals remaining non-diabetes status for 6 years, those with diabetes had higher total cholesterol levels and more frequent use of insulin or oral hypoglycaemics (p < 0.05) and a higher BMI, blood pressure, glucose levels, and percentage of smokers (p < 0.05)." (PMID 38980837, 2024). "However, although studies conducted with AID systems show improvements in glycemic outcomes regardless of gender, age group, duration of diabetes, previous insulin delivery method, or baseline HbA1c levels, they don’t contain data on the effect on food intake." (PMID 38459160, 2024). "In diabetes, serum OGF levels are elevated, and insulin may affect the OGF-OGFr axis." (PMID 38534414, 2024). "Taken together, these data confirm the idea that the risk of severe hypoglycemia upon religious intermittent dry fasting is increased in subjects treated with insulin or with poorly controlled diabetes but is less or not relevant for subjects without diabetes or with well-controlled type 2 diabetes." (PMID 39203800, 2024). "A more recent study evaluated the effects of 35 g of fermented and non-fermented chokeberry in type 2 diabetes mellitus patients, and no statistically significant influence was recorded in terms of waist circumference, insulin sensitivity or fasting levels of glucose, insulin or glucagon." (PMID 39330724, 2024).